ISL2 (ISL LIM homeobox 2)
Description:
Transcriptional factor that defines subclasses of motoneurons that segregate into columns in the spinal cord and select distinct axon pathways.
Synonyms: FLJ10160
Tractability: PROTAC: ubiquitination databases record sites on it.
Gene: Protein-coding gene on chromosome 15 (76,336,773 to 76,342,475, forward strand). Ensembl gene ENSG00000159556.
Subcellular location: Nucleus
Subcellular location (Human Protein Atlas): Rods & Rings
Gene Ontology:
Molecular function: protein binding; sequence-specific double-stranded DNA binding; cis-regulatory region sequence-specific DNA binding; DNA binding; DNA-binding transcription factor activity, RNA polymerase II-specific; sequence-specific DNA binding
Biological process: axonogenesis; neuron development; neuron fate specification; peripheral nervous system neuron development; positive regulation of transcription by RNA polymerase II; regulation of DNA-templated transcription
Cellular component: chromatin; nucleus
Genetic constraint (gnomAD): Loss-of-function variants: 14 observed, 24.31 expected, observed/expected ratio (o/e) 0.58, 90% interval 0.38 to 0.9. The upper end of that interval is the gene's LOEUF score, 0.9, which puts it in group 3 of 6, group 1 being the genes least tolerant of losing a copy. Missense variants: 397 observed, 382.98 expected, observed/expected ratio (o/e) 1.04, 90% interval 0.95 to 1.13. Synonymous variants: 193 observed, 168.54 expected, observed/expected ratio (o/e) 1.15, 90% interval 1.02 to 1.29.
Homologues: Orthologues: chimpanzee ISL2 (100% identical), macaque ISL2 (99% identical), mouse Isl2 (99% identical), rat Isl2 (98% identical), pig ISL2 (98% identical), guinea pig ISL2 (94% identical), rabbit ISL2 (90% identical), zebrafish isl2a (88% identical), zebrafish isl2b (86% identical), tropical clawed frog isl2 (75% identical), dog ISL2 (61% identical), Drosophila melanogaster tup (59% identical), and 1 more. Paralogues in human: ISL1 (74% identical).
Diseases named in the same sentence as ISL2 in open-access papers:
ISL2 is named in the same sentence as 11 diseases in open-access papers, as found by Europe PMC text mining. Sharing a sentence is not in itself a finding about the gene and the disease. The quoted sentences say what the papers report.
oligodendroglioma (3 papers, 2022). A well-differentiated (WHO grade II), diffusely infiltrating neuroglial tumor, typically located in the cerebral hemispheres. "In oligodendroglioma, it was found that under hypoxia, Insulin Gene Enhancer Protein (ISL2) induces angiogenesis by enhancing the expression of Ang2 to promote the growth, malignant transformation and invasion of oligodendroglioma." (PMID 35874764, 2022). "Anti-ISL2 therapy is also a potential treatment option for malignantly transformed oligodendroglioma." (PMID 35965581, 2022). "ISL2 expression and ISL2-mediated angiogenic pathway activity are ideal biomarkers for the malignant transformation of oligodendroglioma." (PMID 35965581, 2022). "In Low-grade glioma (LGG) patients, including oligodendroglioma patients, overexpression of ISL2 was correlated with poor prognosis, and this correlation was not affected by gender or isocitrate dehydrogenase 1(IDH1) mutation status." (PMID 35965581, 2022). "We showed that the expression of insulin gene enhancer protein (ISL2) and its angiogenic ability were positively correlated with the progression of oligodendroglioma." (PMID 35965581, 2022). "When ISL2 expression was found to be reduced, oligodendroglioma cell proliferation was reduced." (PMID 36588901, 2022). "TMZ combined with anti-ISL2 therapy may be effective in oligodendroglioma in vitro and tumor-bearing animal models." (PMID 36588901, 2022).
glioma (2 papers, 2020 to 2022). A benign or malignant brain and spinal cord tumor that arises from glial cells (astrocytes, oligodendrocytes, ependymal cells). "ISL2 was also highly enriched in the IDH wildtype glioma, and was associated with decreased survival rates among different WHO grade glioma in the CGGA datasets." (PMID 32894165, 2020). "Together, these results suggested that ISL2 was elevated in glioma and was associated with poor patient survival." (PMID 32894165, 2020). "In glioma tissues and cells, miR-342-3p is regulated by circ_ARF1, forming a feedback loop composed of U2AF2, ARF1, ISL2, and miR-342-3p, which modulates glioma development." (PMID 36120594, 2022). "To characterize the expression and functions of ISL2 in gliomas, we first searched its expression in CGGA datasets." (PMID 32894165, 2020). "Compared to WHO grade II and grade III glioma, ISL2 expression was higher in glioblastoma (GBM; WHO grade IV)." (PMID 32894165, 2020). "Compared to the normal brain tissues, all qPCR, western blotting, and immunohistochemistry results showed that ISL2 expression was higher in glioma tissues, and was especially increased in higher glioma WHO grades." (PMID 32894165, 2020). "Taken together, these results suggest that cARF1 regulates ISL2 expression via a miR-342–3p-mediated ceRNA mechanism, and promotes gliomas angiogenesis by upregulating ISL2 expression in GSCs." (PMID 32894165, 2020). "We therefore conclude that the oncogenic effects of ISL2 in glioma involved promotion of angiogenesis." (PMID 32894165, 2020). "We then characterized the expressions of ISL2 in our 70 glioma patients, 10 normal brain tissues, and patient-derived primary GSCs." (PMID 32894165, 2020). "In the present study, we first identified ISL2 as a novel oncogene in glioma, which was overexpressed and mainly involved in glioma angiogenesis via VEGFA-mediated ERK signaling, according to both bioinformatics analyses and molecular experiments." (PMID 32894165, 2020). "We then detected the expression of miR-342–3p in our clinical glioma specimens and found its expression was negatively correlated with ISL2 expression in each WHO grade of glioma." (PMID 32894165, 2020). "In this study, we first showed that ISL2 was overexpressed in glioma and correlated with poor patient survival using bioinformatics analysis and our clinical specimens." (PMID 32894165, 2020). "Kaplan-Meier survival analyses showed that the median survival times of lower grade glioma (LGG) patients, GBM patients, or total glioma patients with higher ISL2 expressions were all shorter than in patients with lower ISL2 expression levels." (PMID 32894165, 2020). "The results showed there was a positive association with “GO_POSITIVE_REGULATION_OF_VASCULAR_ENDOTHELIAL_ GROWTH_FACTOR_PRODUCTION” signatures in ISL2 high expression glioma." (PMID 32894165, 2020). "Taken together, these results showed that the U2AF2/cARF1/miR-342–3p/ISL2 axis regulated glioma tumorigenesis and angiogenesis in nude mice." (PMID 32894165, 2020). "As a transcriptional component mainly involved in the development and function of motor and sensory neurons, it is reasonable that ISL2 may exert possible effects on the central nervous system and glioma." (PMID 32894165, 2020). "Finally, we performed orthotopic xenografts to determine the effects of the U2AF2/cARF1/miR-342–3p/ISL2 axis in glioma tumorigenesis and angiogenesis in vivo." (PMID 32894165, 2020). "Our study therefore identified a U2AF2/cARF1/miR-342–3p/ISL2 feedback loop in GSCs, which promoted glioma angiogenesis, and which may provide novel targets for glioma therapy." (PMID 32894165, 2020). "ISL2 was overexpressed in glioma and correlated with poor patient survival." (PMID 32894165, 2020). "As a transcription factor involved in development of the nervous system, it is doubtful whether ISL2 affects the development and progress of glioma." (PMID 32894165, 2020).
glioma (continued). "Moreover, because anti-angiogenic treatment, represented by anti-VEGF therapy, such as bevacizumab, is one of the most important strategies for glioma treatment, ISL2 may act as a possible therapeutic target." (PMID 32894165, 2020). "To determine the possible effect of ISL2 on glioma, we performed gene set enrichment analysis (GSEA) of ISL2 expression based on TCGA and CGGA datasets." (PMID 32894165, 2020). "We also performed Pearson’s correlation analyses between cARF1 and ISL2 mRNA expressions among our glioma specimens, and found that there were strong positive correlations in each WHO grade glioma and overall in all glioma samples." (PMID 32894165, 2020). "Finally, both Cox univariate and multivariate analyses showed that ISL2 expression, WHO grades, and IDH status were independent prognostic factors of glioma patients." (PMID 32894165, 2020). "Although there has been no previous study on the regulation between miR-342–3p and ISL2, miR-342–3p has been reported to play an anti-tumor role in several cancers including glioma." (PMID 32894165, 2020). "Furthermore, U2AF2 bound to and promoted the expression of cARF1, while ISL2 also transcribed the expression of U2AF2, which formed a feedback loop and possibly participated in the malignant transformation of glioma." (PMID 32894165, 2020). "However, there has been no study of the possible effects of ISL2 on cancers, including glioma." (PMID 32894165, 2020). "Finally, we detected the mRNA expression of CD31 in our glioma specimens, and found that there were positive correlations between CD31 and cARF1, ISL2 and U2AF2, while there was a negative correlation between CD31 and miR-342–3p." (PMID 32894165, 2020).
Anxiety (1 paper, 2015). Intense feelings of nervousness, tension, or panic often arise in response to interpersonal stresses. "As the behavioral output in several tasks (e.g., visual cliff, Go/No-Go and Morris water maze) can be modulated by levels of anxiety, they were determined in the Isl2-EphA3 knock-in mice using the light/dark box test." (PMID 24647754, 2015).
Central hypothyroidism (1 paper, 2023). A type of hypothyroidism due to an insufficient stimulation of an otherwise normal thyroid gland. "Homozygous or compound heterozygous ISL2 mutations in central hypothyroidism patients have not been detected thus far." (PMID 36824359, 2023).
tumor (5 papers, 2020 to 2023). "Immunohistochemistry was performed to detect the effects of the U2AF2/cARF1/miR-342–3p/ISL2 axis on tumor tissues." (PMID 32894165, 2020). "Compared to the control group, the tumor volumes were enlarged in the ISL2 overexpression and U2AF2 overexpression groups, and decreased in the miR-342–3p-mimic and cARF1-knockdown groups." (PMID 32894165, 2020). "Moreover, ISL2 overexpression combined with the miR-342–3p mimic group also showed enlarged tumor volumes, while it was decreased in the U2AF2-overexpression combined with the cARF1-knockdown group." (PMID 32894165, 2020). "A low expression of the ISL2 appeared to be of good prognosis, regardless of the type of grade 3 tumor." (PMID 36077653, 2022).
cancer (3 papers, 2013 to 2021). A tumor composed of atypical neoplastic, often pleomorphic cells that invade other tissues. "Our study showed that ISL2 shared a similar oncogenic role as its family member, ISL1, in other cancers." (PMID 32894165, 2020). "Furthermore, 3 out of 10 were epigenetically regulated by PRC2 in ES cells (TWIST1, ISL2 and SIM2), suggesting an important role of methylation events on these genes affecting cell differentiation processes and cancer." (PMID 23468990, 2013).
ISL2 also shares sentences with these, for which no sentence is quoted: Cognitive impairment (1 paper); congenital heart defects (1); glioblastoma (1); low grade glioma (1); respiratory failure (1).